YTHDF1 (YTH N6-methyladenosine RNA binding protein F1)
Diseases named in the same sentence as YTHDF1 in open-access papers (continued):
Sharing a sentence is not in itself a finding about the gene and the disease.
tumor (continued). "EBNA1 facilitates the degradation of the METTL3 protein via the K48-linked ubiquitin pathway, reducing TLR9 m6A modification and YTHDF1-enhanced translation, thus promoting tumor immune evasion." (PMID 39695216, 2024). "The deletion of YTHDF1 can turn ‘cold tumours’ into responsive ‘hot tumours’, increasing the effectiveness of ICI." (PMID 39135292, 2024). "The loss of METTL3 inhibits YTHDF1-mediated SPRED2 translation and further enhances the activation of NF-kB and STAT3 through the ERK pathway, ultimately mediating tumor growth and metastasis." (PMID 39759516, 2024). "The knockout of YTHDF1 in DCs enhances the cross-presentation of tumor antigens in vivo and the cross-activation of CD8+ T cells." (PMID 39759516, 2024). "Our murine models further revealed that administration of cell lines overexpressing YTHDF1 enhanced tumour growth, elevated Ki67 expression, and increased lung metastasis." (PMID 38683130, 2024). "YTHDF1 boosts the synthesis of lysosomal proteases by recognizing the m6A mark on their mRNA, potentially accelerating the breakdown of tumor antigens internalized by dendritic cells." (PMID 39372415, 2024). "In mouse melanoma models, YTHDF1 deficiency restricts lysosomal protease expression in DCs, enhancing cross‐presentation and allowing CD8+ T cells to respond more efficiently to tumour cells." (PMID 39135292, 2024). "The expression of YTHDF1 and miR-16-5p (a miRNA) are post-transcriptionally inhibited and promoted, respectively, by tumor hypoxia, which also induces Hypoxia Inducible Factor 1 (HIF1) through transcription." (PMID 39342406, 2024). "Pertinently, knocking down of YTHDF1 inhibits tumorigenicity in vitro and effectively suppresses murine xenograft tumor growth in vivo, by disrupting the Wnt/β-Catenin pathway." (PMID 39342406, 2024). "Overall, the data indicated that elevated expression of YTHDF1 was correlated with poor prognosis and tumor-infiltrating lymphocyte." (PMID 39557826, 2024). "In traditional DCs, YTHDF1 deletion improves in vivo cross‐presentation of tumour antigens and cross‐priming of CD8+ T lymphocytes." (PMID 39135292, 2024). "Findings from the Ythdf1-knockout mice, CRC cell lines, and primary CRC organoids demonstrated that YTHDF1 executes its pro-tumorigenic impacts by enhancing tumor growth, migration, invasion, and metastasis." (PMID 39136000, 2024). "After YTHDF1 silencing, tumor burden was obviously alleviated, and fewer metastatic nodes were presented in lung tissues sectioned from mice injected with YTHDF1 deficient cells compared with the control group." (PMID 38001065, 2023). "The studies revealed that YTHDF1 activated Wnt/beta-catenin pathway, which was dependent on the maintenance of ISCs in tumor progression." (PMID 36707507, 2023). "YTHDF1-silenced mice show improved tumor antigen cross-presentation by DCs and antitumor responses by CD8+ T cells." (PMID 37485079, 2023). "METTL3 has also been found to direct the m6A methylation of JAK1 mRNA in tumor-infiltrating myeloid cells (TIMs), and the m6A/YTHDF1 axis has been shown to promote JAK1 translation." (PMID 37217462, 2023). "YTHDF1, as an upstream gene of GLS, is closely associated with the reprogramming of glutamine metabolism in tumor cells." (PMID 38202722, 2023). "Knockdown of YTHDF1 promotes the cross-presentation of tumor antigen and the cross-priming of CD8+ T cells via translation of lysosomal cathepsins in Dendritic Cells whereas inhibition of cathepsins significantly increases cross-presentation by wild-type DCs." (PMID 36650570, 2023). "In accordance, another research showed that YTHDF1 was downregulated by miR-136-5p to suppress tumor progression and chemoresistance to 5-FU and OXA, while miR-136-5p was targeted by circPTK2 and declined in CRC cell lines and tissues." (PMID 36810281, 2023). "The YTHDF1 knockdown showed a reduction in tumor number and an inhibition of tumor growth in the AOM/DSS-induced CRC mouse model." (PMID 37152066, 2023).
tumor (continued). "More importantly, to target oncogenic YTHDF1 in vivo, we developed an exosome-induced CRISPR/Cas9 delivery system, which led to YTHDF1 depletion and restored tumor immune surveillance." (PMID 36650153, 2023). "Nevertheless, the crosstalk between tumor-intrinsic YTHDF1 and the immune microenvironment remains to be fully elucidated, given that tumor cell-intrinsic mechanisms are the key factors contributing to the evasion of immune surveillance." (PMID 36650153, 2023). "YTHDF1 plays a crucial role in tumor resistance, leading to a decrease in the effectiveness of chemotherapy and impacting patient prognosis." (PMID 38202722, 2023). "In gastric cancer, METTL3-mediated SPHK2 m6A modification followed by YTHDF1 facilitates translation initiation through interacting with eIF3a, which in turn upregulates the translation efficiency and promotes tumor progression." (PMID 36830614, 2023). "Silenced YTHDF1 in DCs restrained lysosomal proteolysis and promoted the cross-presentation of tumor antigens, leading to promoted cross-priming of CD8 + T cells and enhanced therapeutic efficacy of anti-PD-L1." (PMID 36810108, 2023). "YTHDF1 is found to be highly expressed in the majority of tumors compared to normal tissues, exerting a promotional role in tumor development." (PMID 38202722, 2023). "The results showed that priming with WTA from Ythdf1 KO cells exerts a robust antitumor effect as evidenced by reduced tumor volume, improved survival rate and increased immune cell infiltration." (PMID 36650153, 2023). "In conclusion, YTHDF1 holds tremendous potential in tumor therapy, and the combination of YTHDF1 inhibitors with ICI treatment presents a highly effective therapeutic approach." (PMID 38202722, 2023). "Given the promoting role of YTHDF1 in various tumor types, the search for and development of small molecule inhibitors specifically targeting YTHDF1 have emerged as a crucial approach in the treatment of tumor progression." (PMID 38202722, 2023). "Among them, YTHDF1 serves as a pivotal member, playing a crucial role in protein translation, tumor proliferation, metabolic reprogramming of various tumor cells, and immune evasion." (PMID 38202722, 2023). "And deletion of YTHDF1 in ISCs shrinks tumor size and prolongs the lifespan of CRC-formed mice substantially." (PMID 36999016, 2023). "A recent study has indicated that YTHDF1 is highly expressed in BRCA tumor tissue, creating a “cold” tumor microenvironment by suppressing the release of pro-inflammatory cytokines Ccl7, Il-17rb, Sell, Cxcl2, and Tnfsf4 in BRCA cells." (PMID 38202722, 2023). "The m6A methylation recognition protein YT521-B homology domain family protein 1 (YTHDF1) regulates the tumor immune microenvironment." (PMID 37737134, 2023). "In line with the RNA-seq data, the protein levels of cytokines were upregulated in Ythdf1-KO tumor tissues." (PMID 36650153, 2023). "YTHDF1 also recognizes m6A-marked lysosomal protease mRNAs, thus mediating the decay of neoantigens and bolstering tumor suppressive immunotherapy." (PMID 37086786, 2023). "As presented in Tsuchiya K’s research, m6A RNA methylation regulators, including YTHDF1 and YTHDF2 are associated with better patient survival and therapeutic targets related to the tumor-immune microenvironment in non-small cell lung cancer." (PMID 37194014, 2023). "Here, we reveal that tumor-intrinsic YTHDF1 drives immune evasion and immune checkpoint inhibitor (ICI) resistance." (PMID 36650153, 2023). "YTHDF1 recognizes the m6A modification of lysosomal protease transcription and promotes its expression, which in turn blocks cross-presentation of tumor antigens by DC and antigen-specific activation of CD8+ T cells." (PMID 37178254, 2023). "Tumor-infiltrating lymphocytes from Ythdf1-KO tumors were highly enriched in activated effector T-cell populations, which were assigned largely to the CD8+ TEM, and proliferating CD8+ T-cell states." (PMID 36650153, 2023).
tumor (continued). "To reveal immune microenvironment heterogeneity at single-cell resolution, we performed single-cell transcriptome analysis of tumor-infiltrating CD45+ immune cells from Ythdf1-KO (n = 3) and WT (n = 3) tumors." (PMID 36650153, 2023). "Among them, YTHDF1 has been shown to be involved in the cross-priming of tumor antigens in dendritic cells and the cross-activation of CD8+ T cells." (PMID 38066436, 2023). "Many cancer cell lines and tumours globally overexpress modified RNA and in Ythdf1−/− mice, tumour neoantigen cross-presentation is reduced resulting in impaired immune evasion." (PMID 36513580, 2023). "YTHDF1 exerted an important role in the tumor microenvironment (TME) and YTHDF1 knockdown increased antigen-specific CD8 + T cell antitumor effects." (PMID 36707507, 2023). "In this review, we elucidate the latest signaling pathway mechanisms of YTHDF1 in various tumor cells, with a special emphasis on its distinctive characteristics in tumor cell metabolic reprogramming." (PMID 38202722, 2023). "Such an enhanced cross-priming capacity of CD8+ T-cells was attributed to the improved antigen presentation by DCs (as assessed by the abundance of H-2Kb-SIINFEKL complexes on DCs from wild-type and Ythdf1−/− mice bearing B16-OVA tumours)." (PMID 38136940, 2023). "A study has shown that RANBP2 was identified as a critical target of YTHDF1, and YTHDF1 inhibited the apoptosis of tumor cells by regulating the expression of RANBP2 in CC." (PMID 37951987, 2023). "YTHDF1 exerts its regulatory role in tumor iron metabolism through various signaling pathways by modulating the functions associated with m6A modification." (PMID 38202722, 2023). "Knockdown of YTHDF1 inhibits GC cell proliferation and tumor growth whereas YTHDF1 promotes GC progression via translation of FZD7 in an m6A-dependent manner and activation of the Wnt/β-catenin pathway." (PMID 36650570, 2023). "The expression of YTHDF1 is not only the highest in normal immune cells but also dramatically correlated with tumor immune-infiltrated cells in cancer, especially CD8+ T cells, macrophages, and dendritic cells (DCs)." (PMID 36999016, 2023). "YTHDF1 has been demonstrated to be a potential predictive marker in gastrointestinal tumors, exerting a significant impact on tumor occurrence, metastasis, and prognosis." (PMID 38202722, 2023). "Mechanically, YTHDF1 promoted tumor progression and metastasis of GC by promoting USP14 translation." (PMID 36707507, 2023). "To confirm the importance of YTHDF1 in the defective suppressive functions of USP47-deficient Tregs, we performed IBD induction and tumor inoculation using 6-week-old WT mice, Usp47fl/flFoxp3-Cre mice, and Usp47fl/flYthdf1fl/flFoxp3-Cre mice." (PMID 37788092, 2023). "Together, these results demonstrated that exosome-mediated YTHDF1 depletion was a safe approach to suppress tumor growth by activating the antitumor immune response." (PMID 36650153, 2023). "YTHDF1 deletion strengthens the anti-tumor effect of PD-1 blockers by restoring the infiltration of CD8+T cells." (PMID 37737134, 2023). "In human cancers, YTHDF1 is more highly expressed than in normal tissues and plays an important role in the tumor microenvironment, participating in immune regulation." (PMID 38066436, 2023). "Aberrant expression of YTHDF1 correlated with more aggressive tumor phenotype and poor clinical prognosis." (PMID 37194014, 2023). "Depletion of YTHDF1 amplifies DC-mediated anti-tumor immune response including CD4+ and CD8+ T cells infiltration with increased IFN-γ secretion." (PMID 37015927, 2023). "Our results reveal a role for YTHDF1-mediated m6A-based c-Myc translation in Treg metabolism and homeostasis and identify YTHDF1 as a critical mediator of tumor-induced immune tolerance and a potential therapeutic target to improve tumor immunotherapy." (PMID 37788092, 2023).
tumor (continued). "Another report also revealed that genetic ablation of YTHDF1 obviously blocked Wnt-related tumor gression with reduced intestinal stem cells (ISC) stemness." (PMID 36707507, 2023). "Investigation of the upstream regulatory mechanisms of YTHDF1 dysregulation helps us to better comprehend the biological role of YTHDF1 in cancers and provides possible therapeutic targets for anti-tumor therapy." (PMID 36650570, 2023). "YTHDF1 was significantly increased in CRC tissues compared with adjacent non-tumor tissues, and the copy number gain/amplification of YTHDF1 contributes to its upregulation in CRC." (PMID 37152066, 2023). "With continuous advancements in ferroptosis research, the crucial role of YTHDF1 in tumor iron metabolism has garnered significant attention." (PMID 38202722, 2023). "In endometrial cancer, reduced METTL3 expression leads to a decrease in m6A modification on PHLPP2 mRNA, resulting in attenuated YTHDF1-mediated translation of PHLPP2, which in turn caused de-repression of the AKT pathway and promotes tumor progression." (PMID 36830614, 2023). "YTHDF1 depletion accelerates tumor antigen presentation and cross-priming of CD8+ T cells by retarding lysosomal cathepsin translation in DCs in an m6A-dependent manner." (PMID 36999016, 2023). "YTHDF1 downregulation results in decreased tumor sphere formation and compromised cancer stemness properties." (PMID 38072944, 2023). "Z scores revealed that YTHDF1 expression was differentially enriched between the tumor groups, and most patients with PD had a positive z score." (PMID 36650153, 2023). "And in NSCLC, the depletion of YTHDF1 will decrease the translation efficiency of m6A-modified transcripts, which inhibits tumor growth under normoxic conditions." (PMID 37437245, 2023). "A research team has utilized nanoparticle-encapsulated YTHDF1-siRNA to enhance anti-tumor immunity in CD34 humanised CRC mouse model." (PMID 37965577, 2023). "YTHDF1 is found to regulate the cross-presentation of tumor antigens in DCs and cross-priming of CD8 + T cells." (PMID 36707507, 2023). "Recently, an analogous result has shown that METTL3-deficiency in macrophages destroyed the translation of SPRED2 mediated by YTHDF1, which promoted tumor growth and metastasis through the activation of ERK and NF-κB/STAT3 pathways." (PMID 36960074, 2023). "The YTHDF1 can hyperactivate cancer cell proliferation and tumor progression in colon and gastric cancers." (PMID 37833468, 2023). "Deletion of YTHDF1 enhances the anti-tumor activity of CD8+T cells and inhibits the translation efficiency of lysosomal histone proteases in dendritic cells (DCs)." (PMID 37737134, 2023). "To elucidate the biological functions of tumor-intrinsic YTHDF1 in tumorigenesis and immune evasion, we initially used the CRISPR/Cas9 gene editing system to deplete Ythdf1 gene in the B16/F10 cell line." (PMID 36650153, 2023). "Our findings illustrate that tumor-intrinsic YTHDF1 drives immune evasion via lysosomal degradation of tumor antigen and MHC-I." (PMID 36650153, 2023). "YTHDF1 was supposed as a novel target to deal with chemoresistance in BC and a putative tumor promotor." (PMID 36810281, 2023). "A heatmap of RNA-seq data showed that most of the interleukin family and chemokine family were upregulated in Ythdf1-KO tumor tissues." (PMID 36650153, 2023). "We believe that YTHDF1 represents a highly promising target for future tumor treatments and a novel tumor biomarker." (PMID 38202722, 2023). "PDAC is a highly stromal-rich tumor, and the differential expression of RNA m6A modification, represented by YTHDF1, plays a significant role in prognostic evaluation in both tumor cells and stromal cells." (PMID 38202722, 2023). "The m6A-binding protein YTHDF1 facilitates tumor immune escape by impairing the cross-presentation of tumor neoantigens and cross-priming of CD8+ T cells." (PMID 36263422, 2022).
tumor (continued). "In this study, we analyzed the role of YTHDF1 in GC cells and modulation of the tumor immune microenvironment." (PMID 35193930, 2022). "As a main cytoplasmic m6A reader, YTH domain family 1 (YTHDF1) has been reported to promote translation of target transcripts by recruiting translation initiation factors that affect tumor progression in several cancers." (PMID 36439881, 2022). "Compared with wild-type, in YTHDF1-/- mice, due to the enhanced ability of dendritic cells to present tumor neoantigens, the antigen-specific anti-tumor response mediated by CD8 + T cells is enhanced." (PMID 35303965, 2022). "We observed that proportion of MDSCs in tumor and in infiltrating immune cells were significantly repressed in YTHDF1 knockout tumors as compared with control tumors." (PMID 35193930, 2022). "Multiple lines of evidence have implicated the role of YTHDF1 in EMT, a critical step in tumor metastasis." (PMID 35884552, 2022). "By calculation, we found that the mean YTHDF1 IHC score was significantly higher in tumor samples than in the paracarcinoma group." (PMID 35401696, 2022). "Subsequently, we explored the difference in expression between tumor tissues and adjacent tissues of PAAD and observed that WTAP was notably downregulated in tumor tissues, whereas RBM15, IGFBP1/3, and YTHDF1 seemed upregulated in tumor samples." (PMID 35606813, 2022). "Using mean mRNA expression of YTHDF1 in tumor tissues as cut-off, the Kaplan-Meier curves showed that high YTHDF1 mRNA expression was significantly correlated with poor survival for patients with GC in our cohorts 1 (n=101, p=0.0164)." (PMID 35193930, 2022). "YTHDF1 suppresses dendritic cells presenting neoantigens to T lymphocytes and promotes tumor cell immune escape by promoting lysosomal-related degradation of neoantigens." (PMID 35606813, 2022). "In a melanoma cancer mouse model, tumor regression was found more frequently in anti-PD-L1-treated YTHDF1 knockout mice than in anti-PD-L1-treated wild-type mice." (PMID 36479088, 2022). "The deletion of YTHDF1 inhibits the Wnt-β-catenin signaling pathway, thereby inhibiting tumorigenicity and tumor growth." (PMID 36360287, 2022). "Meanwhile, we also identify that YTHDF1 is involved in the hypoxia-enabled tumor promotion effect, for which the hypoxic tumor microenvironment can inhibit the expression of endogenous miR-16-5p and up-regulate the expression of YTHDF1." (PMID 35319018, 2022). "This implies that tumor promoting effect of YTHDF1 is, at least in part, dependent on a functioning immune system." (PMID 35193930, 2022). "For example, YTHDF1 enhances the antitumor response of tumor-infiltrating CD8+ T cells, thereby promoting tumorigenesis and progression and leading to poor prognosis." (PMID 35186164, 2022). "For example, YTHDF1 interacts with the elongation factor eEF-2 in tumor cells, leading to m6A-induced translational elongation of Snail mRNA, a key transcription factor inducing epithelial-mesenchymal transition (EMT)." (PMID 35884552, 2022). "Loss of YTHDF1 restores sensitivity to antitumor immunity via the recruitment of DCs, which in turn activates CD4+ and CD8+ T cells, culminating in tumor remission." (PMID 35193930, 2022). "YTHDF1 can shape HCC tumor microenvironment and potentiate the adaptation of HCC cells to promote their survival." (PMID 35884552, 2022). "The results demonstrated that CBLL1, ELAVL1 and YTHDF1 expressed more in tumor samples than in normal samples of LUAD and LUSC patients, while the expression level of ZC3H13 in tumor samples is lower than in normal samples of LUAD and LUSC patients." (PMID 36261786, 2022). "This indicates that the coexpression network of YTHDF1 plays an important role in tumor proliferation and development." (PMID 35401696, 2022). "We also analyzed the GEO ESCA cohort and conducted in vitro experiments, which further proved that the expression of YTHDF1 in tumor samples was significantly higher than that in normal samples." (PMID 35401696, 2022).